PLK1 (polo like kinase 1)
Diseases named in the same sentence as PLK1 in open-access papers (continued):
Sharing a sentence is not in itself a finding about the gene and the disease.
aneuploidy (1 paper, 2019). Chromosomal disorder consisting of the presence a chromosomal abnormality in which there is an addition or loss of chromosomes within a set. "In summary, all Plk1 mouse models (either a gain or loss of function) ultimately lead to aneuploidy and CIN." (PMID 30862113, 2019).
Arthritis (1 paper, 2014). Inflammation of a joint. "In the study analyzing its effects on arthritis, 15d-PGJ2 mediated shear-induced chondrocyte apoptosis via protein kinase A (PKA)-dependent regulation of PLK1." (PMID 24566468, 2014). "Interestingly, in arthritis, 15d-PGJ2 mediated shear-induced chondrocyte apoptosis via protein kinase A (PKA)-dependent regulation of PLK1." (PMID 24566468, 2014).
Bloom syndrome (1 paper, 2019). Bloom syndrome (BSyn) is a rare chromosomal breakage syndrome characterized by a marked genetic instability associated with pre- and postnatal growth retardation, facial sun-sensitive telangiectatic erythema, increased susceptibility to infections, and predisposition to cancer. "To validate the immunofluorescence staining results, we examined Bloom’s syndrome fibroblast cells stably expressing a GFP-tagged BLM, and RPE1 cells expressing a GFP-tagged PLK1." (PMID 31253795, 2019).
cerebral infarction (1 paper, 2025). An ischemic condition of the brain, producing a persistent focal neurological deficit in the area of distribution of the cerebral arteries. "The results of TTC staining experiments showed that OTUD3 knockout aggravated cerebral infarction in MCAO/R mice, and treatment with PLK1‐IN‐6 resulted in a further increase in cerebral infarction volume in mice mediated by OTUD3 deletion." (PMID 40462502, 2025).
cervical adenocarcinoma (1 paper, 2020). An adenocarcinoma arising from the cervical epithelium. "We also endeavored to delve into the molecular mechanism of PLK1 in CESC and cervical adenocarcinoma through exploring the mutation and genetic alteration of PLK1 and functional enrichment analysis of correlated genes." (PMID 33354424, 2020). "The intersection of 412 upregulated DEGs and 3898 genes that showed positive correlation with PLK1 (r > 0, adjusted P < 0.05) in RNA-seq dataset generated 177 genes positively correlated with PLK1 in cervical adenocarcinoma." (PMID 33354424, 2020). "Expression matrix of PLK1 in cervical adenocarcinoma was extracted from GSE52904_GPL6244 and RNA-seq dataset from TCGA database." (PMID 33354424, 2020). "The clinic-pathological significance of PLK1 in cervical adenocarcinoma." (PMID 33354424, 2020). "Particularly, pathways such as cell cycle, DNA replication, homologous recombination were commonly shared by positively-correlated genes of PLK1 in CESC and cervical adenocarcinoma." (PMID 33354424, 2020). "PLK1 exhibited concurrent upregulation in CESC or cervical adenocarcinoma samples compared with non-cancer tissues, which was a significant feature in the discrimination of cancer from non-cancer tissues." (PMID 33354424, 2020). "None of these studies compared PLK1 expression in both cervical squamous cell carcinoma versus non-cancer cervix tissues and cervical adenocarcinoma versus non-cancer cervix tissues." (PMID 33354424, 2020). "No common part was found between 267 downregulated DEGs and 81 genes that showed negative correlation with PLK1 (r < 0, adjusted P < 0.05) in RNA-seq dataset of cervical adenocarcinoma." (PMID 33354424, 2020). "We are the first group to compare PLK1 expression between CESC and cervical adenocarcinoma tissues and to evaluate PLK1 expression in CESC versus non-cancer and cervical adenocarcinoma versus non-cancer tissues." (PMID 33354424, 2020). "To sum up, we proved overexpression of PLK1 in CESC versus non-cancer and cervical adenocarcinoma versus non-cancer samples via multiple detection technologies." (PMID 33354424, 2020).
cervical squamous cell carcinoma (1 paper, 2020). A squamous cell carcinoma arising from the cervical epithelium. "The clinic-pathological significance of PLK1 in cervical squamous cell carcinoma (CESC)." (PMID 33354424, 2020).
chlamydial infection (1 paper, 2015). "Moreover, it is known that CEP170 is phosphorylated through Polo-like kinase 1; but how the phosphorylation of CEP170 is involved in the formation or activities of the IPAM–CEP170 complex or influences chlamydial infection remains unknown." (PMID 26220855, 2015).
chordoma (1 paper, 2022). Chordomas are rare malignant tumors arising from embryonic remnants of the notochord in axial skeleton. "Considering that several genomic analyses of chordoma samples reveal widespread cell cycle dysregulation, testing the inhibition of PLK1 in chordomas makes sense." (PMID 36505864, 2022). "Here, we evaluated the tumor efficacy of the CDK4/6 inhibitor palbociclib, as well as the PLK1 inhibitor volasertib, in three chordoma patient-derived xenograft (PDX) models to validate and identify novel therapeutic approaches." (PMID 36505864, 2022).
chronic hepatitis C (1 paper, 2023). "PLK1 expression is increased in liver tissues from people with chronic hepatitis C compared with an uninfected liver (P < 0.05) (GEO dataset GSE15331)." (PMID 37648284, 2023).
clear cell sarcoma (1 paper, 2025). A rare malignant neoplasm with melanocytic differentiation characterized by the presence of polygonal or spindle shaped clear cells. "have shown that in clear cell sarcoma, the expression of the EWS‐ATF1 fusion gene led to increased levels of AURKA and PLK1." (PMID 39789853, 2025).
cystic kidney disease (1 paper, 2012). A congenital or acquired kidney disorder characterized by the presence of renal cysts. "This is the first study linking Plk1 with primary cilia and with the NPH protein complex suggesting a potential function of Plk1 in the pathogenesis of the cystic kidney disease NPH." (PMID 22701722, 2012).
diffuse midline glioma (1 paper, 2024). A diffuse glioma that arises from the midline structures of the central nervous system. "Other groups have also demonstrated a synergistic effect of simultaneously blocking AURKA and PLK-1 in preliminary studies in diffuse midline glioma, paving the way for this promising combinatorial strategy to be translated into clinical trials." (PMID 39684470, 2024).
Ebola (1 paper, 2013). "In addition, Tekmira Pharmaceuticals has developed TKM-PLK1 that targets polo-like kinase 1 (PLK1) for solid tumors and TKM-Ebola to treat Ebola virus infection." (PMID 24300520, 2013).
endometrial tumors (1 paper, 2025). "IHC staining results showed that compared with the control mice, onvansertib treatment significantly reduced the expression of Ki-67 by 44.01%, Plk1 expression by 40.6%, and Bcl-xL expression by 27.23%.in endometrial tumors." (PMID 40166466, 2025).
endothelial dysfunction (1 paper, 2022). In vascular diseases, endothelial dysfunction is a systemic pathological state of the endothelium (the inner lining of blood vessels) and can be broadly defined as an imbalance between vasodilating and vasoconstricting substances produced by (or acting on) the endothelium. "The deregulation of the KLF14/PLK1 cascade plays a crucial role in thrombin-induced endothelial dysfunction in T2DM patients." (PMID 36046788, 2022).
endotoxemia (1 paper, 2023). "Treatment with a selective PLK1 kinase inhibitor suppressed IL-1β production in in vivo inflammatory models, including LPS-induced endotoxemia and monosodium urate–induced peritonitis in mice." (PMID 37698938, 2023).
Follicular Cyst (1 paper, 2004). Cyst due to the occlusion of the duct of a follicle or small gland. "Follicular cysts, present in some but not all ovaries, showed strong staining for PLK1 in theca externa cell layer and served as internal positive control." (PMID 14970859, 2004).
graft versus host disease (1 paper, 2022). An immune system disorder that occurs after allogeneic hematopoietic stem cell transplant and is a reaction of donor immune cells against host tissues. "Interestingly, PLK1 was shown to be upregulated on alloreactive T cells in graft-versus-host disease and blocking its expression prevented T-cell activation and induced apoptosis." (PMID 34605719, 2022).
Hypertension (1 paper, 2025). The presence of chronic increased pressure in the systemic arterial system. "However, overactivation of the PLK-1 → RhoA → actomyosin pathway may contribute to pathological vascular remodeling and hypertension by increasing vascular resistance and promoting excessive smooth muscle contraction." (PMID 41227386, 2025).
ischemia (1 paper, 2021). A hypoperfusion of the BLOOD through an organ or tissue caused by a PATHOLOGIC CONSTRICTION or obstruction of its BLOOD VESSELS, or an absence of BLOOD CIRCULATION. "While overexpression of PLK1 relieved the myocardial infarction and myocardium apoptosis through inducing mitophagy in rats model of ischemia reperfusion." (PMID 34115550, 2021). "In this study, we found that the expression of PLK1 in myocardium of rats was inhibited after the rats suffered from ischemia reperfusion." (PMID 34115550, 2021). "In addition, the expression of mitophagy-related proteins mito LC3 II and Beclin1 was inhibited in myocardium of ischemia reperfusion model and H9c2 cells, which was rescued by overexpression of PLK1." (PMID 34115550, 2021). "Therefore, the expression of mitophagy-related proteins was detected by western blotting to investigate the influence of PLK1 on mitophagy in ischemia reperfusion induced myocardial infarction model and H9c2 cells." (PMID 34115550, 2021). "However, the efficacy and mechanism of PLK1 affecting ischemia-induced myocardial injury remain elusive." (PMID 34115550, 2021).
ischemia reperfusion injury (1 paper, 2021). Adverse functional, metabolic, or structural changes in ischemic tissues resulting from the restoration of blood flow to the tissue (reperfusion), including swelling; hemorrhage; necrosis; and damage from free radicals. "Results showed that the expression of PLK1 was suppressed in myocardium of rats suffered from ischemia reperfusion injury." (PMID 34115550, 2021).
leukoplakia (1 paper, 2017). A white patch or plaque on a mucous membrane that cannot be characterized clinically or pathologically as any other disease. "In conclusion, PLK1 is a promising drug target for chemopreventive trials to eradicate high risk preneoplastic fields, and to prevent tumors in leukoplakia patients and local relapses in treated HNSCC patients." (PMID 29228663, 2017).
liver disease (1 paper, 2023). "Finally, we looked for the effects of viral hepatitis versus nonviral liver disease on PLK1 expression in the liver." (PMID 37648284, 2023).
malignant mesothelioma (1 paper, 2011). A malignant neoplasm of the pleura or peritoneum, arising from mesothelial cells. "In a similar work, a DNA-chimeric siRNA was generated against Plk1, which was more stable in human serum than nonchimeric siRNA and the chimeric Plk1-siRNA inhibited malignant mesothelioma (MM) cell proliferation through the induction of apoptosis in vitro." (PMID 21955150, 2011).
mesenchymal tumors (1 paper, 2019). "In four animal NSCLC models, mesenchymal tumors were more sensitive to Plk1 inhibition alone than were epithelial tumors." (PMID 31040125, 2019).
mesothelioma (1 paper, 2021). A usually malignant and aggressive neoplasm of the mesothelium which is often associated with exposure to asbestos. "We also found previously unrecognised deletions in RB1 in 26% of cases and show sub-micromolar responses to downstream PLK1, CHEK1 and Aurora Kinase inhibitors in primary mesothelioma cells." (PMID 34580349, 2021).
myocardial hypertrophy (1 paper, 2024).
myocardial infarction (1 paper, 2021). Gross necrosis of the myocardium, as a result of interruption of the blood supply to the area, as in coronary thrombosis. "However, overexpression of PLK1 relieved the ischemia reperfusion induced myocardial infarction and myocardial apoptosis in rats." (PMID 34115550, 2021).
obliterative bronchiolitis (1 paper, 2020). "In this study, we identified PLK1 as a promoter of myofibroblast differentiation and investigated the mechanism by which its inhibition alleviates transplant-associated obliterative bronchiolitis (OB) during CAD." (PMID 32541091, 2020).
oligodendroglioma (1 paper, 2022). A well-differentiated (WHO grade II), diffusely infiltrating neuroglial tumor, typically located in the cerebral hemispheres. "Co-deletion of 1p and 19q, a genomic hallmark of oligodendroglioma, more frequently appeared to be associated with the PLK1-low cluster." (PMID 36618405, 2022).
pancreatic (1 paper, 2018). "siRNA targeting PLK1 was found to inhibit the proliferation of pancreatic cancer cells." (PMID 29295989, 2018).
Parkinson disease (1 paper, 2021). A progressive degenerative disorder of the central nervous system characterized by loss of dopamine producing neurons in the substantia nigra and the presence of Lewy bodies in the substantia nigra and locus coeruleus. "Corynoxine can regulate several kinases, including RPS6KB1, MAP2K2, and PLK1, contributing to the clearance of AD-associated β-amyloid precursor protein (APP) and Parkinson disease-associated α-synuclein." (PMID 33807157, 2021).
pterygium (1 paper, 2021). A wedge-shaped fibrovascular lesion arising from the bulbar conjunctiva and extending to the cornea. "In addition, PLK1, which regulates the activity of RAD51, was identified as highly expressed in pterygium." (PMID 34769520, 2021).
schistosomiasis (1 paper, 2012). An infectious disease caused by parasitic trematodes of the genus Schistosoma that colonize human blood vessels and release eggs that can cause granulomatous reactions leading to acute (swimmer's itch or acute schistosomiasis syndrome) or chronic disease. "BI2536 (the first-in-class prototype Plk1 inhibitor) inhibited SmPlk1 kinase activity and induced in vitro dramatic alterations in schistosome gonads, which affected oogenesis and spermatogenesis, suggesting that SmPlk1 could represent a new target against schistosomiasis." (PMID 22768216, 2012).
schwannoma (1 paper, 2025). A benign, usually encapsulated slow growing tumor composed of Schwann cells. "Similarly, Polo-like kinase 1 (PLK1) has been identified as a crucial driver of proliferation in MPNST and Schwannoma cell lines." (PMID 41463204, 2025).
scrapie (1 paper, 2020). A fatal disease of the nervous system in sheep and goats, characterized by pruritus, debility, and locomotor incoordination. "In addition, the brains of scrapie-affected hamsters show evidence of cell cycle activity with an increase in the proteins polo-like kinase (PLK) 1 and cyclin B1, and a decrease in PLK3 and Cdc25C." (PMID 32108870, 2020).
seminoma (1 paper, 2015). A radiosensitive malignant germ cell tumor found in the testis (especially undescended), and extragonadal sites (anterior mediastinum and pineal gland). "At the molecular level, we also detect decreased Gravin, Aurora A, and Plk1 levels in several samples collected from seminoma patients." (PMID 26406118, 2015). "We discover a macromolecular complex between the scaffolding protein Gravin/AKAP12 and the mitotic kinases, Aurora A and Plk1, that is down regulated in human seminoma." (PMID 26406118, 2015). "Therefore, we postulate that abnormalities in Gravin expression that promote mislocalization of Aurora A and Plk1 contributes to defects in orientation of mitotic spindles to potentiate seminoma progression." (PMID 26406118, 2015).
soft tissue sarcoma (1 paper, 2022). A malignant neoplasm arising from muscle tissue, adipose tissue, blood vessels, fibrous tissue, or other supportive tissues excluding the bones. "Recently, PLK1 was proposed as a target for the treatment of the five solid tumor types including soft tissue sarcoma, where application of potent PLK1 inhibitor showed limited antitumor activity in recruited patients." (PMID 36435816, 2022).
Splenomegaly (1 paper, 2024). Abnormal increased size of the spleen. "Additionally, severe splenomegaly was observed in the PLK1 inhibitor-treated group, and flow cytometry analysis revealed a significant increase in erythroblast populations in the spleen." (PMID 39763588, 2024).
systemic lupus erythematosus (1 paper, 2025). An autoimmune multi-organ disease typically associated with vasculopathy and autoantibody production. "The most enriched pathways in the GSE109857 dataset were the cell cycle checkpoints, PLK1 pathway, systemic lupus erythematosus, and TYROBP causal network in microglia." (PMID 41438761, 2025).
Ureteral obstruction (1 paper, 2023). Obstruction of the flow of urine through the ureter. "The present study showed that Polo-like kinase 1 (Plk1) was upregulated in the kidneys of CKD patients and mice subjected to unilateral ureteral obstruction (UUO) with location in proximal tubules and tubulointerstitial fibroblasts." (PMID 37640723, 2023).
urinary system tumors (1 paper, 2023). "Furthermore, based on the very good compliance observed, the administration of Plk1 inhibitors might also be very feasible in patients with non-specific tumors, respiratory system tumors, musculoskeletal system tumors, and urinary system tumors." (PMID 36845678, 2023). "Plk1 inhibitors work better in improving OS and they are well tolerated, effective and safe in reducing the severity of illness while improving the quality of life, especially in patients with non-specific tumors, respiratory system tumors, musculoskeletal system tumors, and urinary system tumors." (PMID 36845678, 2023).
urothelial carcinoma (1 paper, 2023). A malignant neoplasm derived from the transitional epithelium of the urinary tract (urinary bladder, ureter, urethra, or renal pelvis). "PLK1 expression effectively predicted the outcomes in urothelial carcinoma patients in the IMvigor210 cohort after anti-PD-L1 therapy, and thus warrants further exploration as a predictive biomarker of immunotherapy response." (PMID 38186570, 2023).